PIK3CA (phosphatidylinositol-4,5-bisphosphate 3-kinase catalytic subunit alpha)
Diseases named in the same sentence as PIK3CA in open-access papers (continued):
Sharing a sentence is not in itself a finding about the gene and the disease.
breast cancer (continued). "Notably, treatment with either of these two inhibitors in combination with fulvestrant has shown to prolong progression-free survival against fulvestrant alone in patients with ER/PR positive and HER2 negative advanced breast cancer harboring PIK3CA- or AKT1-mutated or PTEN loss." (PMID 39448637, 2024). "In summary, our in vitro data suggest that GluOC accelerates the metastasis of MDA-MB-231 breast cancer cells by promoting ROCK1/MYPT1/MLC2 signalling, and by promoting breast cancer cell proliferation via the ROCK1/JAK2/PIK3CA/AKT signalling pathway." (PMID 39054484, 2024). "We selected three PIK3CA-mutant (MCF7, EFM-19, and T-47D) and two PIK3CA-wildtype PTEN-lost (ZR-75-1 and CAMA-1) ER+ breast cancer cell lines for the study." (PMID 39409880, 2024). "Studies have shown that two crucial genes of this pathway, PI3K catalytic subunit α (PIK3CA) and phosphatase and tensin homolog PTEN are the most frequently altered ones in breast cancer." (PMID 36244040, 2023). "Despite the attention of researchers on PIK3CA, alpelisib (BYL-719) is the only p110α inhibitor that is FDA-indicated for use in breast cancer and only in conjunction with fulvestrant, an estrogen receptor antagonist." (PMID 36900375, 2023). "Herein, we revealed that KAT7 upregulates PIK3CA, leading to activation of the PI3K/AKT signaling pathway, thus promoting radioresistance in breast cancer." (PMID 36724120, 2023). "A preclinical study shows that CDK 4/6 inhibitors increase the sensitivity of PIK3CA-mutant breast cancer cells to PI3K inhibitors, and the combination of the two drugs has a synergistic effect on the treatment of breast cancer." (PMID 36671478, 2023). "GDC‐0077, another selective PI3Kα inhibitor, fared better as a single agent, having a confirmed ORR of 20% in PIK3CA‐mutant, HR‐positive, HER2‐negative breast cancer patients." (PMID 38037839, 2023). "For breast cancer patients, known oncogenes and tumor suppressor genes such as ESR1, KRAS, PIK3CA, PIK3R1, FAT1, and MED12 were consistently identified in both ctDNA and tumor WES across patients." (PMID 37878600, 2023). "Endometrial cancer (Endo), breast cancer (BRCA), and lung squamous cell carcinoma (LUSC) are among the top five cancer types with PIK3CA alterations (cBioPortal for Cancer Genomics)." (PMID 37290530, 2023). "Thus, not all PIK3CA-mutated breast cancer models might benefit from AKT blockers, as some may promote cell growth through an AKT-independent axis, such as PDK1/SGK3/mTORC1." (PMID 36901954, 2023). "We selected a panel of PIK3CA mutant (KPL4, JMT1, and HCC1954) and PIK3CA WT (SKBR3 and BT474) HER2+ breast cancer cell lines." (PMID 37469415, 2023).
breast cancer (continued). "DDR1 depletion inhibits cell growth and cell cycle progression and enhances the sensitivity of PIK3CA/AKT1 mutant cells to palbociclib in estrogen receptor (ER)-positive, HER2-negative breast cancer." (PMID 37709489, 2023). "NEDD4L has been identified as an E3 ligase that mediates the ubiquitination and downregulation of PIK3CA, the catalytic subunit of class IA PI3Ks, thereby inhibiting the PI3K-AKT signaling pathway and VEGFA secretion in breast cancer." (PMID 38027016, 2023). "Currently, a clinical trial is underway to assess the safety, tolerability, pharmacokinetics, and efficacy of HS‐10352 in combination with fulvestrant in patients with PIK3CA‐mutant, HR‐positive, HER2‐negative advanced breast cancer (NCT05504213)." (PMID 38037839, 2023). "It has been demonstrated that oncogenic PIK3CA mutations may contribute to more resistance to antibody-based therapeutic trastuzumab and anti-HER2 agent lapatinib (a dual tyrosine kinase inhibitor blocking HER1 and HER2 tyrosine kinase activity) treatment in breast cancer." (PMID 37237509, 2023). "For example, the SOLAR‐1 trial investigated the combination of alpelisib and fulvestrant in patients with PIK3CA‐mutant, HR‐positive, HER2‐negative breast cancer." (PMID 38037839, 2023). "Therefore, regulating the expression of PIK3CA may help improve breast cancer development." (PMID 36016606, 2022). "However, the differences in the analytical performance of NGS and RT-PCR, the selection of the most appropriate tissue sample (i.e., primary site vs. metastasis), and the stability of PIK3CA mutations over the course of the disease have not been well documented so far in breast cancer." (PMID 36428975, 2022). "These target genes were crossed with breast cancer-related genes in the GeneCards database and differential genes in the TCGA database, and two target genes were finally obtained: PTEN and PIK3CA." (PMID 36497344, 2022). "Several genetically modified mouse strains have been generated to model the role of the PI3K/AKT pathway in breast cancer, including mammary-specific knockout of PTEN, mammary-specific expression of mutant PIK3CA, or myristoylated AKT1." (PMID 35681625, 2022). "Alpelisib demonstrates tolerable safety and favorable clinical efficiency in patients with PIK3CA-altered, HR-positive, HER2-negative breast cancer in combination with fulvestrant or letrozole." (PMID 36209184, 2022). "In some cases, biopsies were taken many years before the participant entered the FAKTION trial, but the original tumour PIK3CA, AKT1, and PTEN status appeared to define the efficacy of capivasertib for advanced breast cancer." (PMID 35671774, 2022). "Prospective studies of the biomarkers PIK3CA and germline BRCA1/2 alterations in breast cancer drive the approval of the targeted drugs PI3K inhibitor and PARP inhibitor." (PMID 36397030, 2022). "On the other hand, the PIK3CA mutation in SSC, apart from its utility in molecularly defining the precise tumor type, could also be used as a molecular target as has been seen in another solid tumor such as in breast cancer and its associated guided-therapy alpelisib plus fulvestrant." (PMID 36010253, 2022). "When counted together, 71.8% of breast cancers, which include 42.1% PPAPA and 29.7% PPAPA/TP53I tumors, contain the PTEN-PI3K-AKT1 pathway activated by genomic alterations of Pten, PIK3CA (H1047R & E545K), and AKT1 (E17K)." (PMID 34975329, 2022).
breast cancer (continued). "Given the substantial overlap of PIK3CA status in primary tumors and metastases, the choice of what sample to test in HR+/HER2− breast cancer should be primarily driven by the quality and quantity of FFPE material available, regardless of the anatomical site." (PMID 36428975, 2022). "Reactivation of additional p110 isoforms such as p110β has also been shown to sustain PIP3 accumulation and attenuate the growth inhibitory effect induced by p110α inhibition in PIK3CA-mutant and HER2-amplified breast cancer cells." (PMID 33809714, 2021). "The patient with the highest increase in activity of COX-2, PIK3CA, HER2, and Vimentin was diagnosed with colon cancer 84 months after treatment of breast cancer." (PMID 34590615, 2021). "However, alpelisib with letrozole for the neoadjuvant treatment of HR+/HER2– early breast cancer patients reported no improvement in ORR regardless of whether the patients have PIK3CA mutation." (PMID 34026830, 2021). "miR-152-3p has been identified as a tumor suppressor; for example, miR-152-3p was observed to negatively regulate PIK3CA expression, thus inhibiting the activation of AKT and RPS6 in breast cancer cells." (PMID 34336125, 2021). "In vivo studies showed a marked anti-proliferative and pro-apoptotic activity towards human breast cancer cell lines with PI3K pathway alterations, sufficient to induce a dose-dependent tumor growth delay or regression in PIK3CA-mutant xenografts." (PMID 34298731, 2021). "The PIK3CA detection rates in basal-like (38.24%, 13/34) were higher than in luminal B (31.67, 19/60), HER2+ (30.61%, 15/49), and luminal A (26.98 %, 17/63) breast cancers." (PMID 33893247, 2021). "In advanced luminal breast cancer, CDK4/6 inhibitors demonstrated a remarkable improvement in PFS and OS, and recently, the biomarkers PIK3CA and BRCA have defined a new strategy of treatment." (PMID 34680350, 2021). "The analysis of the data contained in TCGA confirmed the lower level of PIK3CA, PIK3R1 and PTEN gene expression in breast cancer tissues compared to normal tissues and a higher level of AKT1 gene." (PMID 33669698, 2021). "Conversely, in PIK3CA-mutant PTEN wild-type prostate and breast cancers, p110α inhibition provides superior antiproliferative effects." (PMID 34417459, 2021). "To provide a comprehensive model for evaluating potential drugs for treating PIK3CA/PTEN–wild‐type, HER2‐positive, trastuzumab‐resistant breast cancer, we established xenograft tumors in zebrafish and immunodeficient mice." (PMID 33665980, 2021).
breast cancer (continued). "Ipatasertib, another AKT inhibitor which was initially tested in TNBC, has been evaluated in HR-positive, HER2-negative advanced breast cancers through the IPATunity 130 randomized phase III trial, among patients with PIK3CA/AKT1/PTEN altered tumors." (PMID 34948307, 2021). "We report PIK3CA-mutant ER+ breast cancers exhibit increased INPP4B mRNA and protein expression and INPP4B increased the proliferation and tumor growth of PIK3CA-mutant ER+ breast cancer cells, despite suppression of AKT signaling." (PMID 34035258, 2021). "The genomic examination of breast cancer includes testing for HER2 amplification and PIK3CA activation." (PMID 34681592, 2021). "The analysis of the data contained in TCGA confirmed a lower level of PIK3CA, PIK3R1 and PTEN gene expression in breast cancer tissues compared to normal tissues and a higher level of the AKT1 gene." (PMID 33669698, 2021). "A cBioPortal analysis shows ≈50% of breast cancers with genomic aberrations in PIK3CA, AKT1, AKT2, AKT3, and/or ESR1,suggesting relevance of this signaling axis in breast cancer." (PMID 33498407, 2021). "In addition, although the frequency of PIK3CA variants in exons 9 and 20 is high in both elderly and young patients, some of these variants may not be pathogenic in the context of breast cancer." (PMID 34287479, 2021). "In breast cancer, miR-10a was determined to interrupt PI3K/Akt activation via targeting phosphatidylinositol-4,5-bisphosphate 3-kinase catalytic subunit alpha (PIK3CA), hence acting as a tumor-suppressive miRNA to suppress breast cancer progression." (PMID 33066509, 2020). "In preclinical models of BM in breast cancer, HER3 has been found to be overexpressed in BM compared to primary tumors in HER2-amplified and/or PIK3CA mutant breast tumors." (PMID 32093103, 2020). "Alpelisib has been reported to improve the survival patients with PIK3CA-altered, ER-positive, HER2-negative breast cancer." (PMID 33004031, 2020). "In this study, BT474 and MDA-MB-361 cell lines were used, which represent PIK3CA-wt and PIK3CA-mut (E545K) ER+/HER2+ breast cancer cell lines, respectively." (PMID 33303839, 2020). "For example, the presence of genomic alterations in genes such as ERBB2, PIK3CA, AKT1, ESR1 and NTRK in advanced breast cancer patients help to stratify patients for targeted therapies." (PMID 33167363, 2020).
breast cancer (continued). "Lymph node positive luminal B tumors were enriched in pathways related to cell proliferation, immune response and cytoskeletal changes such as enrichment of PIK3CA, MAP kinases, NF-κB factors and RHOA, pathways which play role in breast cancer progression." (PMID 32947901, 2020). "We analyzed a publicly available cancer cohort (n = 9052) from cBioPortal to identify alteration frequencies for EGFR, PIK3CA, and PTEN genes across all breast cancer subtypes." (PMID 33148288, 2020). "Routine PIK3CA testing from tissue or ctDNA isolated from plasma samples from patients with HR+/HER2– advanced/mBC is now recommended, as patients with PIK3CA-mutated breast cancer may be appropriate candidates for alpelisib, a recently FDA approved selective inhibitor of the α isoform of PI3Ki." (PMID 32637176, 2020). "Next, we compared the BRF2 Outlier results to known breast cancer biomarkers, HER2 (ERBB2), MYC, PIK3CA, and ER (ESR1) using the same stringent threshold criterion." (PMID 33176745, 2020). "Next, we compared BRF2 overall survival status results with known oncogenes and biomarkers in breast cancer by analyzing the same data set for ERBB2 (HER2), ESR1 (ER), and PIK3CA." (PMID 33176745, 2020). "In breast cancer, SGK3 is amplified and acts as PIK3CA oncogenic effector in a INPP4B phosphatase-dependent manner." (PMID 32296634, 2020). "Identification of cytoplasmic biologic markers in breast cancers, which are proteins that run in the PUKCA/AKT/mTOR pathways, such as PIK3CA, PTEN, pAKT/pS6, metabolites, and aldehyde dehydrogenase 1 (ALDH1), is being widely developed." (PMID 32695508, 2020). "In this review, we discuss the use of PIK3CA as a biomarker to guide treatment decisions in patients with HR+, HER2‐negative advanced breast cancer, as well as practical considerations and recommendations for testing." (PMID 32697890, 2020). "In breast cancers (BRCA), PIK3CA is commonly altered by SMs; in ovarian cancers (OV), it is more often affected by CN amplification; in head and neck squamous carcinoma (HNSC), it is almost equally altered by SMs and CN amplification." (PMID 31276486, 2019). "Increased the expressions of PIK3CA and PTEN mRNA in breast cancer tissue compared to normal breast tissue." (PMID 31554385, 2019). "The MAP2K1, PIK3CA, and RAF1 and especially Raf1 are all believed to be the common suppressors in the breast cancer." (PMID 30906409, 2019). "PIK3CA plays important role in breast cancer treatment, the FDA on May 2019 approved alpelisib (Piqray tablets) to be used in combination with fulvestrant (endocrine therapy) for the treatment of postmenopausal women, and men, with HR+, HER2-, PIK3CA-mutated, advanced or metastatic breast cancer." (PMID 31554385, 2019). "Collectively, these findings provide evidence to support RNMT as a therapeutic target in breast cancer and suggest that therapies targeting RNMT would be most valuable in a PIK3CA mutant background." (PMID 30991934, 2019). "Since role of PIK3CA in tumor growth is essential and EGF activates all oncogenes, it refers to the important impact of EGF in breast cancer." (PMID 34466490, 2019). "Output analysis showed that, in the breast cancer patients, MAP2K1 and PIK3CA have a significant relationship with the occurrence and prognosis of the breast cancer." (PMID 30906409, 2019). "The LOTUS study reported that ipatasertib in combination with paclitaxel improved PFS in patients with PIK3CA/Akt1/PTEN-altered TNBC, suggesting that PIK3CA/Akt1/PTEN alterations can also be biomarkers of response to ipatasertib in patients with breast cancer." (PMID 31227862, 2019).